TRIM26 (tripartite motif containing 26)
Diseases named in the same sentence as TRIM26 in open-access papers (continued):
Sharing a sentence is not in itself a finding about the gene and the disease.
liver fibrosis (10 papers, 2021 to 2024). "It has been indicated that mRNA levels of TRIM26 are significantly downregulated in liver fibrosis tissues." (PMID 38956921, 2024). "For instance, TRIM26 induces HSC ferroptosis to inhibit liver fibrosis by the ubiquitinated degradation of SLC7A11." (PMID 38756248, 2024). "The process is driven by TRIM26-mediated ubiquitination and degradation of SLC7A11, making TRIM26 a promising therapeutic agent against liver fibrosis." (PMID 37867509, 2023). "TRIM26 can inhibit liver fibrosis by mediating the ubiquitination of SLC7A11 and promoting the ferroptosis of hepatic stellate cells (HSCs), which can be used as a new therapeutic strategy for liver fibrosis." (PMID 35478955, 2022). "Overall, these observations reveal that TRIM26 overexpression can mitigate liver fibrosis triggered by CCl4 in mice." (PMID 33869196, 2021). "After ferroptosis-promotive effect of TRIM26 was revealed in vitro, we next designated to examine its protective effect on liver fibrosis in vivo." (PMID 33869196, 2021). "In the study, we investigated the expression of TRIM26 in normal, fibrotic, and cirrhotic liver tissues, and the roles of TRIM26 in HSCs activation and liver fibrosis." (PMID 33869196, 2021). "Collectively, reduction of these critical indicators of liver fibrosis reveals that TRIM26 overexpression inhibits HSCs activation and the fibrogenic process, which facilitated us to explore its underlying mechanism." (PMID 33869196, 2021). "In conclusion, TRIM26 promotes HSCs ferroptosis to suppress liver fibrosis through mediating the ubiquitination of SLC7A11." (PMID 33869196, 2021). "Our findings propose that TRIM26-induced SLC7A11 suppression can be potentially targeted for liver fibrosis treatment." (PMID 33869196, 2021). "Furthermore, TRIM26 protects against hepatic stellate cell activation and thereby alleviates the progression of hepatic fibrosis by mediating SLC7A11 ubiquitination and ferroptosis." (PMID 37821436, 2023). "Trim26 promotes HSC ferroptosis in liver fibrosis by mediating SLC7A11 ubiquitination to inhibit liver fibrosis, which may be a new treatment strategy." (PMID 36276287, 2022). "Moreover, the translational level of TRIM26 is reversely proportional to the severity of liver fibrosis in liver fibrosis animal model, indicating the correlation between TRIM26 expression and liver fibrotic progression." (PMID 33869196, 2021). "In vivo function of TRIM26 in liver fibrosis was examined based on CCl4-induced mice model." (PMID 33869196, 2021). "Overall, this study reveals the potent therapeutic effectiveness of TRIM26 on liver fibrosis, while further study might be necessary to investigate the long-term function of TRIM26 overexpression and the potential adverse effects it may introduce." (PMID 33869196, 2021). "The TRIM26-targeted SLC7A11 suppression can be a novel therapeutic strategy for liver fibrosis." (PMID 33869196, 2021). "In addition, TRIM26 overexpression induced HSCs ferroptosis and mitigated CCl4-induced liver fibrosis in mice." (PMID 33869196, 2021). "Through qRT-PCR anaylsis, we observed that the mRNA level of TRIM26 were significantly different among patient groups; the highest TRIM26 expression was observed in those with mild liver fibrosis, followed by those with severe liver fibrosis and with liver cirrhosis." (PMID 33869196, 2021). "In conclusion, TRIM26 is critical for HSCs ferroptosis to attenuate liver fibrosis." (PMID 33869196, 2021). "Notably, in vivo overexpression of TRIM26 in livers significantly mitigates carbon tetrachloride-induced liver fibrosis progression by suppressing hepatic stellate cells (HSCs) hyperactivation via degradation of solute carrier family-7 member-11 (SLC7A11) and promotion of HSCs ferroptosis." (PMID 37821436, 2023). "Through enhancing the ubiquitination of the Solute Carrier family-7 member-11 (SLC7A11), TRIM26 triggered ferroptosis in Hepatic Stellate Cells (HSC), ultimately reducing liver fibrosis." (PMID 38956921, 2024).
liver fibrosis (continued). "Tripartite motif-containing protein 26 (TRIM26) induces HSC ferroptosis through the regulation of solute carrier family-7 member-11 (SLC7A11) ubiquitination, thereby ameliorating liver fibrosis." (PMID 37007035, 2023). "However, whether TRIM26 participated in HSCs activation and liver fibrosis remains to be clarified." (PMID 33869196, 2021). "Previous research showed that tripartite motif-containing protein 26 (TRIM26), a ferroptosis inducer, promoted ferroptosis in HSCs to inhibit liver fibrosis, which indicated that ferroptosis inducers might be potential anti-fibrosis agents." (PMID 36339568, 2022). "Furthermore, we also demonstrate that TRIM26 overexpression in mice can suppress SLC7A11 and effectively mitigate CCl4-induced liver fibrosis." (PMID 33869196, 2021). "Although the functions of TRIM26 in other forms of HSCs programmed cell death need to be further investigated, the findings from the current study provide novel insights on an SLC7A11-targeted therapeutic approach for hepatic fibrosis." (PMID 33869196, 2021).
bladder cancer (9 papers, 2021 to 2025). "Fourteen TRIM family proteins were associated with bladder cancer (tumor-promoting: TRIM9, TRIM25, TRIM26, TRIM28, TRIM29, TRIM59, TRIM65, and TRIM66; tumor-suppressive: TRIM19 and TRIM38)." (PMID 40723250, 2025). "Knockdown of TRIM26 led to the inhibition of proliferation, migration, and invasion of bladder cancer cells by impeding the AKT/GSK3b/b-catenin pathway." (PMID 38260302, 2024). "In another report, TRIM26 exerted an oncogenic role in bladder cancer and depletion of TRIM26 in bladder cancer cells slowed down tumor progress by inhibiting Akt/GSK3β/β-catenin pathway." (PMID 37591850, 2023). "TRIM26 exerts an oncogenic role in bladder cancer through the regulation of cell proliferation, migration, and invasion via the AKT/GSK3β/β-catenin pathway." (PMID 36261847, 2022). "TRIM26 is also considered a pro-oncogenic protein in bladder cancer." (PMID 37872147, 2023). "And knockdown of TRIM26 could inhibit the proliferation, migration, and invasion of bladder cancer cells." (PMID 35617983, 2022). "TRIM26 exerts an oncogenic effect in bladder cancer via AKT/GSK3β/β-catenin." (PMID 36261847, 2022). "For example, it was demonstrated that TRIM26 had an oncogene impact on bladder cancer through regulating cell proliferation, migration and invasion via the Akt/GSK 3 β/β-catenin pathway, and methylation CpG sites had a significant effect on the regulation of TRIM26." (PMID 34464378, 2021). "Another group showed that TRIM26 expression was increased in human bladder cancer tissues and cell lines, and knocking down TRIM26 significantly inhibited the proliferation, migration, and invasion of bladder cancer cells through the Akt/GSK3β/β-catenin pathway." (PMID 36249749, 2022). "Addressing these questions would help us depict a better image for how TRIM26 acts as a dual player in tumorigenesis and as a potential drug target for future development of anti-cancer therapies, at least for gliomas, CRC, bladder cancer and melanoma." (PMID 38260302, 2024).
glioblastoma (6 papers, 2021 to 2024). The most malignant astrocytic tumor (WHO grade IV). "In further support of this positive relationship between TRIM26 and SOX2, in TCGA glioblastoma samples, we observed a significant correlation between TRIM26 and SOX2 mRNA expression levels, consistent with the ability of SOX2 to stimulate its own transcription." (PMID 34732716, 2021). "We found that the mRNA levels of TRIM26 in glioblastoma (GBM) and low-grade gliomas (LGG) were higher than those in normal brain tissues (NB)." (PMID 37872147, 2023). "TRIM26 interrupts WWP2, a ubiquitin ligase, to prevent SOX2 protein from ubiquitination and degradation in glioblastoma stem cells (GSCs), which maintains the undifferentiated status of GSCs27." (PMID 37604854, 2023). "In glioblastoma, TRIM26 could stabilize SOX2 protein, a pluripotency transcription factor, by inhibiting the interaction of SOX2 with its targeting E3 ubiquitin ligase WWP2 to promote the tumorigenicity of glioblastoma stem cells." (PMID 38773612, 2024). "Fascinatingly, TRIM26 was found to stabilize SOX2 protein and enhance its oncogenic activity in glioblastoma via its C-terminal PRYSPRY domain without engaging its Ring domain and E3 ligase activity." (PMID 38260302, 2024).
schizophrenia (6 papers, 2013 to 2024). A major psychotic disorder characterized by abnormalities in the perception or expression of reality. "In a separate group of individuals with schizophrenia (n = 202), TRIM26 exhibited differential expression and is regarded as a potential gene associated with schizophrenia." (PMID 38956921, 2024). "In addition, neuroinformatic analyses have linked Trim26 to neuropsychiatric disorders such as anxiety disorders, autistic spectrum disorders, bipolar disorder, major depressive disorder, and schizophrenia." (PMID 32093602, 2020).
non-small cell lung carcinoma (5 papers, 2022 to 2024). A group of at least three distinct histological types of lung cancer, including non-small cell squamous cell carcinoma, adenocarcinoma, and large cell carcinoma. "TRIM26 exhibited significant upregulation in non-small cell lung cancer (NSCLC) and facilitated NSCLC cell proliferation and metastasis by inducing K48-linked polyubiquitination of PBX1." (PMID 38773612, 2024). "For example, overexpression of TRIM26 inhibited the growth of non-small cell lung carcinoma cells by suppressing the PI3K/AKT signaling pathway and also, led to suppression of proliferation, metastasis, and growth of papillary thyroid cancer cells." (PMID 38260302, 2024). "TRIM26 is utilized to a certain degree in the study of Non-small Cell Lung Cancer (NSCLC)." (PMID 38956921, 2024).
papillary thyroid carcinoma (5 papers, 2022 to 2024). "On the other hand, over-expression of TRIM26 could suppress the proliferation and metastasis of papillary thyroid carcinoma cells." (PMID 35617983, 2022).
glioma (4 papers, 2023 to 2024). A benign or malignant brain and spinal cord tumor that arises from glial cells (astrocytes, oligodendrocytes, ependymal cells). "Studies have demonstrated that TRIM26 is involved in gliomas by facilitating the K63-linked polyubiquitination of GPX4, a cellular agent that safeguards against ferroptosis." (PMID 38956921, 2024). "Dysregulation of TRIM26 has been implicated in several cancers including glioma, but the molecular mechanisms governing its activation remain to be explored." (PMID 37872147, 2023). "Consistently, immunohistochemical (IHC) assays determined the positive association between TRIM26 expression and glioma grade." (PMID 37872147, 2023). "Taken together, these results indicate that TRIM26 S127 phosphorylation is associated with resistance to ferroptosis in glioma cells." (PMID 37872147, 2023). "Herein, we show that TRIM26 expression is unregulated in glioma, and its overexpression indicates a worse survival outcome." (PMID 37872147, 2023). "Clinically, TRIM26 expression shows a direct correlation with GPX4 and PLK1 levels in glioma samples and is associated with poor outcome in patients with glioma." (PMID 37872147, 2023). "PLK1 inhibition led to ferroptosis in glioma cells by dephosphorylating TRIM26, further resulting in GPX4 degradation." (PMID 37872147, 2023). "In this study, we identified TRIM26 E3 ubiquitin ligase as a key regulator of GPX4 proteasomal degradation in glioma cells." (PMID 37872147, 2023). "Taken together, these data indicate that TRIM26 promotes tumorigenesis of glioma by suppressing ferroptosis via GPX4." (PMID 37872147, 2023). "TRIM26 silencing dramatically impedes ferroptosis resistance and tumorigenesis in glioma in vivo and in vitro." (PMID 37872147, 2023). "Thus, the knockdown of TRIM26 has been found to induce ferroptosis in glioma cells and inhibit their tumorigenic capacity." (PMID 38956921, 2024). "Further investigation revealed that TRIM26 is overexpressed in glioma cells." (PMID 37872147, 2023). "Depletion of TRIM26 could induce ferroptosis and inhibit tumorigenesis of glioma cells, indicating its oncogenic role in glioma." (PMID 37872147, 2023). "Finally, we performed an IHC assay on 83 human glioma samples, and observed that TRIM26 expression was positively correlated with GPX4 and PLK1 protein levels." (PMID 37872147, 2023). "For instance, TRIM26 is overexpressed in glioma and suppresses ferroptosis via the degradation of GPX4, while RNF139 inhibits glioma cell growth through PI3K/AKT signaling in a ubiquitination-dependent manner." (PMID 39075053, 2024). "In vivo, the inhibitory effect of TRIM26 depletion on glioma tumorigenicity was rescued by TRIM26 S127D, but not by TRIM26 S127A." (PMID 37872147, 2023). "Moreover, high expression of TRIM26, GPX4 and PLK1 was correlated with poor survival in patients with glioma." (PMID 37872147, 2023). "Moreover, we found that TRIM26 phosphorylation levels were correlated with PLK1 activity in a panel of glioma cell lines and confirmed endogenous binding between PLK1 and TRIM26, suggesting that PLK1 is a key kinase that targets TRIM26." (PMID 37872147, 2023).
nasopharyngeal carcinoma (4 papers, 2018 to 2024). A carcinoma arising from the nasopharyngeal epithelium. "Research has revealed that the variant of SNP, rs117565607, plays a role in controlling the expression of TRIM26 in nasopharyngeal carcinoma." (PMID 38956921, 2024). "Meanwhile, down-regulated TRIM26 directly attenuated the cytotoxicity and tumor-killing susceptibility of NK cells, thus supporting a mechanism related to immune escape in nasopharyngeal carcinoma with low TRIM26 expression." (PMID 38956921, 2024).
autoimmune disease (3 papers, 2015 to 2022). A disorder resulting from loss of function or tissue destruction of an organ or multiple organs, arising from humoral or cellular immune responses of the individual to their own tissue constituents. "Given the pathological role of IFN-β in SLE and other autoimmune diseases, TRIM26 may be used as a therapeutic target to limit IFN-β overproduction to prevent and cure these diseases." (PMID 25763818, 2015).
clear cell renal cell carcinoma (3 papers, 2024). "Consistent with expectations, the mRNA and protein levels of TRIM26 were significantly elevated in clear cell renal cell carcinoma (ccRCC) cells that were infected with LV-TRIM26, in comparison to the control cells." (PMID 38773612, 2024). "Gain- and loss-of-function tests demonstrated that the overexpression of TRIM26 suppressed cell proliferation, migration, invasion, and the epithelial-mesenchymal transition (EMT) process in clear cell renal cell carcinoma (ccRCC)." (PMID 38773612, 2024). "Nevertheless, the precise role of TRIM26 in clear cell renal cell carcinoma (ccRCC) has not been investigated." (PMID 38773612, 2024).
colorectal cancer (2 papers, 2024 to 2025). A primary or metastatic malignant neoplasm that affects the colon or rectum.
diabetes (2 papers, 2023). "Besides, hypertension and diabetes are linked by CXCL8, HLA-B, and KANSL1; diabetes and obesity are linked by TRIM26 and MMP8; hypertension and obesity are linked by PLA2G7, FSTL3, STC2, and BCL2A1." (PMID 36685671, 2023).
liver cancer (2 papers, 2024). An epithelial or non-epithelial malignant neoplasm that arises from the liver. "In liver cancer, the degradation of β-catenin occurs through ubiquitination, specifically mediated by TRIM26." (PMID 38926362, 2024).